IL23A (interleukin 23 subunit alpha)
Description:
Associates with IL12B to form the pro-inflammatory cytokine IL-23 that plays different roles in innate and adaptive immunity. Released by antigen-presenting cells such as dendritic cells or macrophages, binds to a heterodimeric receptor complex composed of IL12RB1 and IL23R to activate JAK2 and TYK2 which then phosphorylate the receptor to form a docking site leading to the phosphorylation of STAT3 and STAT4. This process leads to activation of several pathways including p38 MAPK or NF-kappa-B and promotes the production of pro-inflammatory cytokines such as interleukin-17A/IL17A. In turn, participates in the early and effective intracellular bacterial clearance. Promotes the expansion and survival of T-helper 17 cells, a CD4-positive helper T-cell subset that produces IL-17, as well as other IL-17-producing cells.
Synonyms: SGRF; IL23P19; IL-23; IL-23A; P19
Tractability: Small molecule: a structure with a bound ligand is known. Antibody: an approved drug acts on it; UniProt places it where antibodies can reach, with high confidence; its Gene Ontology location is reachable by antibodies, with high confidence; UniProt predicts a signal peptide or a membrane-spanning region.
Gene: Protein-coding gene on chromosome 12 (56,334,174 to 56,340,410, forward strand). Ensembl gene ENSG00000110944.
Subcellular location: Secreted
Subcellular location (Human Protein Atlas): Cytosol; Predicted to be secreted
Pathways (Reactome):
Immune System: Interleukin-23 signaling; Interleukin-4 and Interleukin-13 signaling
Gene Ontology:
Molecular function: cytokine activity; interleukin-23 receptor binding; protein binding
Biological process: cell surface receptor signaling pathway via JAK-STAT; cell surface receptor signaling pathway via STAT; defense response to Gram-negative bacterium; interleukin-23-mediated signaling pathway; negative regulation of interleukin-10 production; positive regulation of activated T cell proliferation; positive regulation of defense response to virus by host; positive regulation of granulocyte macrophage colony-stimulating factor production; positive regulation of interleukin-10 production; positive regulation of interleukin-12 production; positive regulation of interleukin-17 production; positive regulation of natural killer cell proliferation; positive regulation of NK T cell activation; positive regulation of NK T cell proliferation; positive regulation of osteoclast differentiation; positive regulation of T cell proliferation; positive regulation of T-helper 1 type immune response; positive regulation of tumor necrosis factor production; positive regulation of type II interferon production; positive regulation of inflammatory response; positive regulation of memory T cell differentiation; positive regulation of natural killer cell activation; positive regulation of non-canonical NF-kappaB signal transduction; positive regulation of T cell mediated cytotoxicity; positive regulation of T-helper 17 cell lineage commitment; and 7 more
Cellular component: extracellular region; interleukin-23 complex; endoplasmic reticulum lumen
Genetic constraint (gnomAD): Loss-of-function variants: 13 observed, 14.73 expected, observed/expected ratio (o/e) 0.88, 90% interval 0.57 to 1.4. The upper end of that interval is the gene's LOEUF score, 1.4, which puts it in group 5 of 6, group 1 being the genes least tolerant of losing a copy. Missense variants: 144 observed, 176.51 expected, observed/expected ratio (o/e) 0.82, 90% interval 0.71 to 0.94. Synonymous variants: 72 observed, 69.13 expected, observed/expected ratio (o/e) 1.04, 90% interval 0.86 to 1.27.
Homologues: Orthologues: chimpanzee IL23A (100% identical), macaque IL23A (98% identical), dog IL23A (88% identical), rabbit IL23A (88% identical), pig IL23A (87% identical), guinea pig IL23A (83% identical), rat Il23a (79% identical), mouse Il23a (75% identical).
Diseases named in the same sentence as IL23A in open-access papers:
IL23A is named in the same sentence as 160 diseases in open-access papers, as found by Europe PMC text mining. Sharing a sentence is not in itself a finding about the gene and the disease. The quoted sentences say what the papers report.
psoriasis (152 papers, 2009 to 2026). An autoimmune condition characterized by red, well-delineated plaques with silvery scales that are usually on the extensor surfaces and scalp. "Recent advances in genetic epidemiology studies have delineated shared susceptibility loci between psoriasis and PsA, such as HLA-B/C, IL23A, IL23R, IL12B, and REL." (PMID 41583484, 2025). "These mice showed upregulated expression of IL-17 and TNF-α signaling-related cytokines and chemokines (e.g., TNF, Ccl20, Cxcl1, IL-22, IL-23a) and are more susceptible to psoriasis upon induction." (PMID 41583484, 2025). "Simultaneously, IDMF represses pro-inflammatory transcription factors, including NF-κB, AP-1, and potentially IRF1, leading to the downregulation of key psoriasis-associated cytokines such as IL-17A, IL-23A, IL-36G, and IFN-γ." (PMID 41465291, 2025). "The cytokine IL-23A, which is typically associated with psoriasis, was found to be down-regulated, thus laying the groundwork for further research into human psoriasis in mice." (PMID 39534602, 2024). "For example, mutations in the IL-12B, IL-23R, and IL-23A genes are associated with both susceptibility to psoriasis and an increased risk of developing diabetes." (PMID 38179048, 2023). "Accordingly, genes associated with psoriasis, including S100a8, S100a9, Camp, Tnf, Il1b, Il23a, and Ccl2, were strongly downregulated." (PMID 35869084, 2022). "Lastly, common DNA variants of IL-12B, IL-23R, and IL-23A were associated with increased susceptibility to psoriasis and contributed to an increased risk of developing T2D in a Spanish population." (PMID 36012327, 2022). "These cytokine-signaling pathways were associated with several psoriasis susceptibility loci such as IL23A, IL23R, and NFKBIZ." (PMID 34680995, 2021). "Correlation (R-values) of IL17A, IL22, and IL23A with genes linked to psoriasis susceptibility through genome-wide association studies." (PMID 31019502, 2019). "We also used this strategy to correlate the expression of IL17A, IL22, and IL23A with genes linked to psoriasis susceptibility identified through genome-wide association studies (GWAS)." (PMID 31019502, 2019). "Correlation (R-values) of IL17A, IL22 and IL23A in psoriasis with genes linked to atopic dermatitis susceptibility through genome-wide association studies." (PMID 31019502, 2019). "Expression of genes linked to psoriasis identified through GWAS and associated IL23A Spearman correlation and p-value and fold change increase in lesional skin and p-value." (PMID 31019502, 2019). "The key role of this axis in psoriasis pathogenesis is strongly supported by the association between IL-23R, IL-12B, and IL-23A gene variants and psoriasis susceptibility." (PMID 27595115, 2016). "SNPs in the TNFAIP3 gene, but also in other immune-regulatory genes including HLA-C, TNIP1/ABIN-1 and IL-23A have been associated to psoriasis and polymorphisms in the TNFAIP3 gene correlate to responsiveness to TNFα blockers in psoriasis patients." (PMID 26124703, 2015). "Recently, a genome-wide scan study in 1,409 psoriasis cases and 1,436 controls revealed associations between three genes of the IL-23 pathway (IL23A, IL23R and IL12B), two genes of nuclear factor-κB (NF-κB) pathway (TNIP1 and TNFAIP3) and psoriasis." (PMID 21555979, 2011). "The suppression of type 17-associated cytokines, particularly IL-17A and IL-23A, through necroptosis inhibition suggests that necroptosis may contribute to psoriasis pathogenesis via type 17 inflammation." (PMID 40332377, 2025). "From a genetical point of view, the overlap between psoriasis and MetS may be explained by IL-12B, IL-23R, and IL-23A gene variants related to psoriasis susceptibility but also to risk for developing type II DM." (PMID 38003284, 2023).
psoriasis (continued). "Molecular analysis of the skin of IgG- and anti-IL36R-treated K14-IL17Aind mice revealed effective suppression of psoriasis-associated cytokines (Il36a, Il36g, Il36b, Il23a, and Tnf), chemokines (Cxcl1, Cxcl5, and Ccl2) and antimicrobial-peptides (such as Defb4) on mRNA level." (PMID 38162658, 2023). "Moreover, genetic variations that encode subunits of cytokines (IL-12B, IL-23A) or cytokine receptors (IL-23R) have been associated with immune disorders such as psoriasis and psoriatic co-morbidities, including Crohn's disease and diabetes." (PMID 22185520, 2011). "For example, the Genetic Analysis of Psoriasis Consortium & the Wellcome Trust Case Control Consortium 2 in a GWAS study for psoriasis, replicated many of the suggestive associations found by Nair and colleagues including SNP nearby IL-23A and TNFIP3 with P≤2×10−5 and P≤1×10−5, respectively." (PMID 22509378, 2012). "In parallel, IDMF suppresses NF-κB, AP-1, IRF1, and STAT-linked pathways, thereby downregulating IL-17A, IL-23A, IL-36G, IFN-γ, and other psoriasis-associated cytokines at their transcriptional origins." (PMID 41465291, 2025). "We thus blocked the proinflammatory cytokines TNF-α, IL-6, IL-1β, and IL-23A, which are known to be crucial to γδ T cell activation, in WT and Acvr1b-Lyz2cre mice during psoriasis." (PMID 40067393, 2025). "A clinical trial supports our study finding where administration of ustekinumab, an anti-IL-23A monoclonal antibody, or brodalumab, or anti-IL-17A blockers resulted in a significant reduction of anxiety and depression symptoms in psoriasis patients." (PMID 38956309, 2024). "We previously reported that both mature and semimature DCs in psoriasis lesional skin expressed high levels of IL23A compared to control skin." (PMID 37781383, 2023). "Originally, only IL23A of immune cell origin was believed to be disease relevant, but recently, it was shown that keratinocyte-produced IL23A in itself is sufficient to initiate psoriasis-like skin inflammation." (PMID 37351597, 2023). "Mice models with IL23A gene deletion restricted to keratinocyte confirm the signification of keratinocyte-derived IL-23A in psoriasis development and show the importance of IL-23 as a biomarker of disease." (PMID 37298466, 2023). "Our current study showed that the expression of IL23A in both mature and semimature DCs was decreased after systemic IL-17A blockade in posttreatment psoriasis lesional skin compared to pretreatment psoriasis lesional skin (p < 0.05)." (PMID 37781383, 2023). "Considering that psoriasis is a Th17-related inflammatory disease, we assessed the expression of Il17a and Il23a in mouse skin tissues." (PMID 38007430, 2023). "COQ10A is upregulated in CAD (FC = 3.76, p = 2.4 × 10−3), while IL23A is upregulated in psoriasis (FC = 6.91, p = 1.8 × 10−10)." (PMID 36323703, 2022). "Both are CAD drug targets, although IL23A is also a drug target for psoriasis, and both have eQTL and mQTL evidence." (PMID 36323703, 2022). "This methodology revealed four distinct T17 cell subsets with a uniquely enriched IL‐17F+ IL‐1− population and a subset of semimature DCs expressing IL‐23A and IL‐36G in psoriasis." (PMID 35196402, 2022). "In psoriasis skin lesions, keratinocytes were the second most prevalent source of IL23A in GSE151177 and the primary source of IL23A in GSE162183." (PMID 35693818, 2022). "There are 122 differentially upregulated and 210 differentially downregulated genes in common between the activated + fisetin and the activated group alone, notably many psoriasis-associated genes such as CCL20, IL36G, IL23A and NFKBIZ." (PMID 36741386, 2022). "Consistent with the ameliorated psoriasis‐like phenotype, the mRNA levels of genes related to the IL‐23/IL‐17 axis, such as Il23a, Il17a, and Il22, and the expression of Tnfa, Il6, and Il1b was decreased in the skin." (PMID 34936223, 2022).
psoriasis (continued). "The present study examines the expression of the genes IL-10, IL-17A, IL-17RA, IL-23A and IL-23R in the skin and peripheral blood of patients with psoriasis and of healthy people, to identify potential factors regulating the development of psoriatic lesions." (PMID 34945130, 2021). "The protein level of IL-23A was significantly decreased in back skin from IMQ-induced psoriasis mice." (PMID 34381369, 2021). "IL-10, IL-17A, IL-17RA (interleukin 17A receptor), IL-23A (interleukin 23 subunit α) and IL-23R (interleukin 23 receptor) in the development of psoriasis." (PMID 34945130, 2021). "Accordingly, blockade of Th17-derived IL-17A and the Th17-inducing cytokine IL-23A are both highly efficacious for skin disease in most patients with psoriasis." (PMID 33117403, 2020). "IL-23A gene transcription levels were previously shown to be higher in the skin of patients with psoriasis than in healthy controls." (PMID 33182442, 2020). "IL-19 has been proposed as a member of the inflammatory IL-23A/IL-17A cascade in psoriasis; its upregulation in keratinocytes is driven by IL-17A, and it acts in an autocrine fashion on keratinocytes to amplify the effects of IL-17A." (PMID 31964744, 2020). "qRT-PCR analysis revealed that unstimulated ear skin from PD-1−/− and WT mice contain similar low levels of psoriasis-related cytokines, IL-6, IL23-A, and IL-17A (P = 0.95, P = 0.57 and P = 0.21 by Mann–Whitney U test, respectively)." (PMID 33060784, 2020). "The baseline serum levels of psoriasis-related cytokines (IL-6, IL-17A, and IL-23A) were the same between WT and PD-1−/− mice (n = 3)." (PMID 33060784, 2020). "A genome-wide association study identified numerous genetic risk factors associated with psoriasis, such as LCE3B, LCE3C, CSTA (involving skin barrier function), IL12B, IL23A, IL23R, TYK2, IFIH1, and ERAP1, and ZAP70 (in immunological response)." (PMID 31736959, 2019). "In contrast, topical Cal was reported to induce CD4+ Tregs in the dLNs32, and we found that Cal and Cal/BDP significantly suppressed the IL-23a expression in psoriasis-like skin lesions." (PMID 31705000, 2019). "In contrast, IL17A clusters together with IL23A and the other cytokines thought to be involved in psoriasis pathophysiology." (PMID 31019502, 2019). "Many genes (e.g., IL-12B, IL-23A, IL-23R, TRAF3IP2, and TYK2) are significantly associated with psoriasis." (PMID 29292715, 2017). "Genetic studies that link single nucleotide polymorphisms in/near IL-23R, IL23A, IL12B, TYK2 and STAT3 with psoriasis susceptibility have highlighted IL-23 as a critical cytokine in disease pathogenesis." (PMID 26573299, 2016). "IL-17 elicits its pro-inflammatory effects in RHE, stimulating the expression of several genes including IL23A, IL1β, and IL36B (IL1F8) that have been implicated in psoriasis pathogenesis and found to be over-expressed in psoriatic lesional skin." (PMID 24587313, 2014). "In support of this, CAP significantly reduced inflammatory cytokines such as IL‐17A, IL‐23A, IL‐24, IL‐1β, and TNFα in psoriasis cells and modulated critical factors in the MAPK pathway in vitro, and led to substantial improvements in factors such as skin thickness, erythema and scaling in vivo." (PMID 40989573, 2025). "Moreover, daphnetin has been revealed to significantly alleviate erythema, scaling, epidermal thickness, and inflammatory cell infiltration in psoriasis-like mice by attenuating upregulation of IL-6, IL-23A, and IL-17A in the skin lesions of mice." (PMID 41462398, 2025). "Researchers have identified STAT3, TYK2, IL23A, and IL23R as susceptibility factors for psoriasis." (PMID 39296901, 2024). "In addition, the genes encoding proteins involved in the nuclear factor κB (NFκB) signaling pathway, including interleukin 12B (IL12B), IL23A, and tyrosine kinase 2 (TYK2), have also been reported as susceptibility genes for psoriasis." (PMID 37511476, 2023).
psoriasis (continued). "In addition, systemic anti-IL-17A monoclonal antibody administration promotes regulatory DCs, while strongly downregulating the expression of IL23A in dendritic cells in psoriasis skin lesions." (PMID 37781383, 2023). "A previous study reported that administration of propranolol (the nonselective beta-blocker) was relevant with exacerbation of psoriasis, ascribed to inhibition of autophagic flux, with an abundance of ROS-producing mitochondria in cutaneous LCs, leading to IL23A production." (PMID 36242051, 2022). "Consequently, SHP2‐mediated TLR7/NF‐κB activation was augmented, leading to further increases in the expressions of psoriasis‐related inflammatory cytokines, including IL‐23A, TNF‐α, IL‐6, and IL‐1β, thus accelerating psoriasis‐like skin inflammation." (PMID 34936223, 2022). "In addition, the IL-23A expression was significantly higher in patients with moderate to severe disease (with PASI > 10) than those with the mild (PASI ≤ 10) form of psoriasis." (PMID 34945130, 2021). "In the present study, IL-23A gene expression was decreased in the psoriasis group and the controls." (PMID 34945130, 2021). "However, daphnetin treatment attenuated IMQ-induced upregulation of those inflammatory cytokines in IMQ-induced psoriasis-like skin lesion at a certain extent, significantly reduced the expression of IL-6, IL-23A and IL-17A." (PMID 33081840, 2020). "Moreover, gene polymorphisms of IL23A, IL23R, STAT3, RUNX3, and TYK2 have also been identified as susceptibility factors for developing psoriasis." (PMID 31649667, 2019). "However, variable relationships amongst the expression of psoriasis susceptibility genes and of IL17A, IL22, and IL23A were identified." (PMID 31019502, 2019). "We prioritized SNP rs79824801 on chromosome 12 as a PFV in IL23A region for psoriasis." (PMID 29715312, 2018). "Moreover, SOC1, IL-12B, IL-23R, TRAF3IP2 and IL23A have been found to be related to the pathway involved in Th17 cell differentiation in psoriasis." (PMID 29232931, 2017). "Moreover, some of the Th17 pathway-related genes, IL-23A subunit, IL-23R, IL23B subunit, have been identified as psoriasis susceptibility genes." (PMID 24587313, 2014). "Furthermore, single-nucleotide polymorphisms (SNPs) in genes involved in IL-23 signaling (IL23A, IL23R, and IL12B) are also associated with psoriasis." (PMID 22229105, 2012). "Our findings indicate that suppressing SIRT3 exacerbated IMQ-induced psoriasis-like inflammation by upregulating the levels of acetylated XBP1s, which subsequently enhanced its total protein levels and transcriptional activity and increased the production of IL-23a, IL-6, and TNF-α cytokines." (PMID 37275851, 2023). "Since our previous data indicated an important role for H3K9 methylation for the regulation of IL-23A expression in mouse keratinocytes, we wanted to test whether this mechanism is also relevant in human keratinocytes and in psoriasis, an IL-23-dependent chronic skin inflammation." (PMID 29650963, 2018). "IL23A, IL4, IL13, and TNFR1 are targets of medically efficacious drugs in widespread use in psoriasis and atopic dermatitis, consistent with the observed enhanced likelihood of success for polygenic disease therapeutics directed at GWAS-linked targets." (PMID 40998781, 2025). "In the present study, we found that CB2R KO contributed to the pathogenesis of psoriasis by promoting CD4+ T cell proliferation; upregulating Th17 cytokines, such as IL-17A, IL-23A, and IL-17C; and downregulating IL-10." (PMID 35173615, 2022). "We further analyzed the correlation between the expression of these regulators and some well-known gene biomarkers of psoriasis (i.e. IL17A, IL17C, IL23A) and measures of disease severity (i.e. the PASI and PSI)." (PMID 35874668, 2022).